PDCD4 (programmed cell death 4)
Diseases named in the same sentence as PDCD4 in open-access papers (continued):
Sharing a sentence is not in itself a finding about the gene and the disease.
tumor (continued). "Taken other line of evidence together, a possible role of miR-21 as an oncogene has been hypothesized, including proliferation, cell cycle, metastasis, and chemosensitivity of tumor cells by targeting several tumor suppressor genes such as PTEN, MARCKS, PDCD4, and Cdc25A." (PMID 22792096, 2012). "In addition, it has been reported to counteract the expression of putative tumor-suppressive targets, such as phosphatase and tensin homolog deleted on chromosome 10 (PTEN), programmed cell death 4 (Pdcd4), tropomyosin 1, maspin and reversion-inducing cysteine-rich protein with kazal motifs." (PMID 20092645, 2010). "We showed that lower PDCD4 expression levels were significantly associated with regional disease (neck nodal metastasis), more advanced tumor stages, and poorer survival and disease-free survival of OSCC patients, suggesting that PDCD4 may have prognostic value in OSCC." (PMID 20831814, 2010). "Especially in skin, although PDCD4 was originally identified as a tumor suppressor in mouse epidermal cell line model and in-depth studies of experimental oncology have been conducted in skin of genetically modified mice, the normal biologic role of PDCD4 in skin has not yet been revealed." (PMID 26703592, 2015). "PDCD4 particularly inhibits the MAP4K1 promoter without affecting other pathways, such as ERK or NF-κB, thereby reducing tumor cell invasion." (PMID 41034525, 2025). "Conversely, upregulation of miRNA-21 has been identified as a negative predictor of tumor progression by regulating PTEN and PDCD4 in PANC-1 and PA-TU-8988S cell lines." (PMID 39200178, 2024). "The anti-tumor activities of resveratrol in PCCs derived from LNCaP and DU145 were found to be equivalent, with the decrease of PDCD4 and Akt, while miR-21 did not influence them." (PMID 37843642, 2023). "PDCD4, located at 11q13 close to MEN1, has been found to be absent in NETs and has been shown to act as a tumor suppressor in neuroendocrine cells." (PMID 28903345, 2017). "Immunohistochemical analysis showed that FBXW7, STK40, and PDCD4 protein was moderately/strongly expressed in the basal/suprabasal cells of ZST esophagus, but reduced or absent in hyperplastic/tumor-bearing ZD3T, ZD6T, and ZD12T esophagus." (PMID 26918602, 2016). "Programmed cell death 4 (PDCD4) is a suppressor of tumorigenesis, tumor progression, and invasion that acts with or without initiator challenge." (PMID 26252635, 2015). "Additionally, we observed a negative correlation between EPCART and PDCD4 in PCa tumor samples, suggesting there to be a subpopulation of PCa tumors, the protein synthesis of which is modulated by EPCART through AKT/mTOR/PDCD4 pathway." (PMID 39147845, 2024). "However, non-tumor lung expression of miR-21, PTEN, MARCKs, TPM-1, PDCD4, and SPRY-2 did not significantly differ between LC-COPD and LC patients." (PMID 29371906, 2018). "However, we observed a negative correlation between the expression of tumor PTEN mRNA, as well as of PDCD4 protein in tumor astrocytes and the level of tumor miR21, supporting the link between miR21 and these targets." (PMID 25986346, 2015).
cancer (273 papers, 2006 to 2025). A tumor composed of atypical neoplastic, often pleomorphic cells that invade other tissues. "Many cancer studies have shown that PDCD4 is a gene known to be associated with promoting apoptosis." (PMID 40461641, 2025). "For instance, the miRNA targets PDCD4, which is linked to the prevention of neoplastic transformation as well as the promotion, invasion, and advancement of cancer." (PMID 39132504, 2024). "PDCD4 is frequently downregulated in many types of cancers, and the loss of its expression has been strongly implicated in the development and progression of several tumors." (PMID 36522523, 2023). "PDCD4 activity is associated with the inhibition of cancer cell proliferation, and it is negatively regulated by the cascade of the mTORC1/p70S6K pathway." (PMID 36552834, 2022). "In particular, knockdown of miR-21 increases translation of proinflammatory tumour suppressor programmed cell death protein 4 (PDCD4), restricts cell proliferation and promotes apoptosis, while high levels of miR-21 are associated with cancer." (PMID 33805674, 2021). "The Trametinib-mediated anti-cancer function was associated with a significantly suppressed level of miR-21, of which primary targets included PDCD4, as shown in this study." (PMID 34885115, 2021). "Several miRNAs, including miR21, have been implicated in the regulation of the expression of PDCD4 and suppression of cancer cell apoptosis." (PMID 31952347, 2020). "Located on chromosome 10q24, the PDCD4 gene plays important roles and its allelic mutations are frequently observed in human cancers." (PMID 33089961, 2020). "It has been found that PDCD4 expression deficiency was closely associated with the progression and prognosis of various cancers, such as the myloid leukemia, lung, ovarian, colon and glima cancers." (PMID 31409387, 2019). "PDCD4 is an oncosuppressor gene whose expression is frequently altered in cancer, causing the disruption of the apoptotic machinery." (PMID 29707109, 2018). "PDCD4 is frequently downregulated in various human cancers; however, the molecular mechanism accounting for the loss expression of PDCD4 in cancers is not fully understood." (PMID 27634902, 2016). "The association between PDCD4 expression and cancer cell differentiation was clearly demonstrated in peripheral blood cancers." (PMID 27852288, 2016). "The PDCD4 gene is located on chromosome 10q24, and its allelic loss/gain is frequently reported in human cancers." (PMID 27852288, 2016). "The tumour suppressor protein Programmed Cell Death Protein 4 (PDCD4) has been implicated in the development of various human cancers and small RNAs such as microRNAs (miRNAs) can regulate its expression." (PMID 26867589, 2016). "This miRNA and others (for example miR-150, miR-182) target the tumor suppressor programmed cell death protein 4 (PDCD4), which has been implicated in the development and progression of several human cancers." (PMID 26867589, 2016). "Several studies have validated that loss of PDCD4 during tumorigenesis promotes cancer cell proliferation, metastasis and inhibits apoptosis." (PMID 27647131, 2016). "In this meta-analysis, we examined the association between PDCD4 expression and the clinicopathologic parameters of cancers from different anatomical sites, including the brain, head and neck, breast, and digestive, gynecologic, and urinary systems." (PMID 27852288, 2016). "Future studies on a larger scale are warranted to address the association of PDCD4 with the unique clinical features presented by different cancers." (PMID 27852288, 2016). "We found that the set of genes regulated by the 11 deregulated miRNAs was enriched for proteins that have key roles in various pathways, such as PTEN/Akt, MAPK, RhoA, FOXO3 and PDCD4 genes, which are causatively deregulated in cancer diseases." (PMID 24788655, 2014).
cancer (continued). "The tumor suppressor Programmed Cell Death 4 (PDCD4) has been found to be under-expressed in several cancers and associated with disease progression and metastasis." (PMID 20831814, 2010). "Recently, Programmed Cell Death 4 (PDCD4) has been strongly associated with the progression and metastasis of multiple human cancer types." (PMID 20831814, 2010). "As a result, loss of PDCD4 confers growth advantages to the cells by several means and thereby facilitates the development of cancer." (PMID 20602797, 2010). "Due to the same inflammatory and metabolic pathways between cancer and AF, deregulation of PDCD4 in certain malignancies might increase the risk of AF." (PMID 40766329, 2025). "Growing evidence links the loss of Pdcd4 to chemotherapy resistance in various cancer types, though the exact mechanism remains unclear." (PMID 39459035, 2024). "Forced up-regulation of Pdcd4 or miR-155 silencing in these neoplastic cancer cells could reduce AP-1-associated transcription of the BIC promoter and reduces expression of miR-155." (PMID 35402235, 2022). "DTL (Denticleless E3 ubiquitin protein ligase homolog) and SKP2 (S-phase kinase-associated protein 2) could degrade cancer progression via PDCD4 ubiquitination." (PMID 33996533, 2021). "Moreover, silencing PDCD4 rescued cancer cell growth and mobility deficiencies caused by DTL knockdown." (PMID 31409387, 2019). "Indeed, the loss of PDCD4 expression has been strongly implicated in the development and progression of several types of human cancers." (PMID 30687637, 2018). "This regulation is particularly important in cancer development because loss of PDCD4 correlates with an increase in the expression of these and other apoptosis-regulating proteins, thus contributing to the cell's ability to evade apoptosis following treatment with chemotherapeutics." (PMID 26595526, 2016). "Moreover, an increase in miR-21 expression has been observed in many cancers, which likely contributes to the frequently observed loss of PDCD4." (PMID 26595526, 2016). "In these cancers, loss of PDCD4 expression was associated with disease progression." (PMID 26867589, 2016). "However, the molecular mechanism accounting for the loss expression of PDCD4 in human cancers is not fully understood." (PMID 27634902, 2016). "In other cancers, PDCD4 was shown to have diagnostic, and prognostic significance." (PMID 20831814, 2010). "Finally, we also found that PDCD4 dysregulation in cancers like ACC may increase AF risk through immune modulation, suggesting that targeting PDCD4 could benefit both AF and ACC patients." (PMID 40766329, 2025). "Loss and gain of function studies in different types of cancer types have established a role for miR-21 in cell proliferation, inhibition of apoptosis, migration, invasion and distant metastasis, and a number of cancer-relevant miR-21 target genes in addition to Pdcd4 and PTEN have been identified." (PMID 23533633, 2013). "The mechanism involves GAS5 functioning as a ceRNA by sequestering miR-21, thus upregulating the expression of pro-apoptotic genes, including PDCD4, and sensitizing cancer cells to cisplatin treatment." (PMID 39958058, 2025). "PDCD4 has been reported to be a target of hsa-miR-21-5p, mainly in the field of cancer research, such as breast and colorectal cancers." (PMID 40461641, 2025). "Prior studies have confirmed that miR-181a directly targets FOXO1 and PDCD4 and that its suppression increases apoptotic sensitivity in various cancers." (PMID 41462911, 2025). "P. gingivalis reduces the activity of PDCD4, which enhances cancer cell stemness and leads to CSC enrichment in ESCC cells." (PMID 40843171, 2025). "Despite the recognized importance of PDCD4 in cancer biology, a comprehensive PDCD4-based gene expression signature for RCC prognosis has not been established." (PMID 41614853, 2025). "In esophageal cancer, P. gingivalis promotes carcinogenesis by reducing PDCD4 activity and enhancing cancer stemness." (PMID 40843171, 2025).
cancer (continued). "The biological effects of PDCD4, as well as its involvement in apoptosis and protein translation regulation, further highlight its significance in cancer biology." (PMID 39891297, 2025). "MiR-21 influences invasion and metastasis through its targets PTEN, TPM1, PDCD4, and the tumor suppressor maspin, making it a potential target for cancer therapy." (PMID 38726321, 2024). "While similar differential distribution of PDCD4 between nuclear and cytoplasmic compartments has been observed before in other cancer cells and has clinical significance in a few other cancers, our results are the first to report the effect in PCa." (PMID 39147845, 2024). "PDCD4, a protein primarily recognized for its central roles in cancer and immune regulation, has garnered significant attention as a therapeutic target." (PMID 38912807, 2024). "Analysis of the Pdcd4 expression level in a panel of NCI-60 cancer cell lines suggested that Pdcd4 protein level contributes to cellular sensitivity to tamoxifen and geldanamycin." (PMID 39459035, 2024). "Although previous studies have shown that PDCD4 suppresses cancer cell growth by inducing apoptosis, recent studies have found that the inhibition of PDCD4 also induces inhibition of cell growth by inducing apoptosis and/or cellular senescence." (PMID 36522523, 2023). "The antiapoptotic effect of miR-21 was partly mediated through its target genes PDCD4, and PDCD4 translational suppression by miR-21 has been demonstrated in the pathobiology of cancer cell proliferation." (PMID 36082081, 2022). "This review highlights the properties of PDCD4 and documents the evidence for the regulation of PDCD4 expression by microRNAs in cancers of the GI tract." (PMID 35847932, 2022). "In this type of cancer, the inhibitory role of miR-21 on PDCD4 has been verified both in vitro and in vivo." (PMID 35402235, 2022). "A recent study characterized the dynamic relationship between PDCD4 and EMT-associated proteins, and the suppression of PDCD4 was correlated with increased cell invasion, a key cancer hallmark." (PMID 36552834, 2022). "DTL interacts with PDCD4 and promotes the ubiquitin-proteasomal degradation of PDCD4, thus enhancing cancer progression." (PMID 35983977, 2022). "The expression of miR-21 was inhibited and ITGβ4 and PDCD4 protein expression was promoted in the cancer cell line by berberine." (PMID 36144625, 2022). "A decrease in PDCD4 expression can be accompanied by the development of malignant tumors, including the lung, colon, liver, and breast tumors, as well as glioblastomas." (PMID 34606825, 2021). "PDCD4 is well-documented to have functional significance depending on its expression as either a nuclear or cytoplasmic protein in multiple cancer types." (PMID 33801444, 2021). "Some previous studies report that, miR-21-5p can specifically repress PDCD4 expression, thus promoting the progression of multiple cancers, including OS." (PMID 34905503, 2021). "As Cui and other researchers found, DTL facilitates cell mobility and proliferation of cancer through degradation of PDCD4, thus promoting the progression of cancer cells." (PMID 34594374, 2021). "Knockdown of PDCD4 was shown to promote resistance to chemotherapy in different types of cancer cells, and PDCD4 was a functional target for miR‐21–induced chemoresistance in tongue squamous carcinoma cells." (PMID 33270982, 2021). "By analogy to PDCD4 function during cancer metastases, decreases in PDCD4 in neurons would function to enable experience-dependent neuronal growth and remodeling." (PMID 34617965, 2021). "The described mechanism of PDCD4 activity in translation termination can be used in the development of therapeutic approaches for the treatment of cancer and other serious diseases in which PDCD4 participates." (PMID 34606825, 2021).
cancer (continued). "Low concentrations of PDCD4 have been reported to correlate with invasion, proliferation, and metastasis of many types of cancers." (PMID 34617965, 2021). "The up-regulation of miR-21 in this cancer induces the silencing of several tumor suppressor genes, such as programmed cell death 4 (PDCD4) and leucine zipper transcription factor-like 1 (LZTFL1)." (PMID 34885130, 2021). "PDCD4 has been studied primarily in the context of cancer, where it has been found to function as a tumor suppressor and translational inhibitor in the cytoplasm." (PMID 34617965, 2021). "In CCA, miR-21 promotes cancer cell proliferation by inhibiting the expression of programmed cell death 4 (PDCD4) and tissue inhibitor of metalloproteinase 3 (TIMP3) by targeting 15-PGDH/HPGD." (PMID 34299246, 2021). "By reducing miR-21 expression within cancer cells, the exercise retrieves PDCD4 and phosphatase and tensin homolog (PTEN) activity and limits the proliferation of cancer cells." (PMID 35083006, 2021). "PDCD4 protein expression is regulated by multiple microRNAs in HNSCC, and loss of PDCD4 renders cancer cells more resistant to cisplatin." (PMID 34070147, 2021). "During this process, exosomal miR-21 derived from cancer cells serves as an intercellular messenger for osteoclast differentiation and function by regulating PDCD4 expression." (PMID 33391543, 2021). "Programmed cell death 4 (PDCD4) induces programmed cell death to reduce the viability of cancer cells." (PMID 32612456, 2020). "Although misregulation of PDCD4 in a variety of tumors suggests an important role in cancer development, the full scope of PDCD4 translational targets and its potential role in other growth-dependent cellular systems has only recently started to be elucidated." (PMID 32747606, 2020). "PDCD4, a target gene of miR-21, has been considered an efficient suppressive regulator in many cancers, including CC." (PMID 32661236, 2020). "Previous work in cancer cells demonstrated that both the translation and activity of PDCD4 can be regulated via the mTOR-p70S6K pathway, prompting us to investigate the potential link between PDCD4 and its upstream regulator p70S6K." (PMID 32747606, 2020). "To elucidate the intricate role of PDCD4 in cancer, we first investigated the mRNA levels of PDCD4 in several cancer types from the TCGA database." (PMID 33304903, 2020). "PDCD4 mRNA is targeted by several microRNAs, most prominently oncogenic microRNA miR-21, whose over-expression in cancer cells down-regulates PDCD4 expression." (PMID 32066800, 2020). "Among the predicted target genes, PDCD4 elicited our interest for its crucial role in the development of multiple human malignant tumors." (PMID 33078826, 2020). "miR-21 suppresses the expression of APAF1 (apoptotic peptidase activating factor 1) and PDCD4 (programmed cell death 4) to inhibit apoptosis and make cancer cells resistant to chemotherapeutics." (PMID 32204455, 2020). "PDCD4 controls the inhibition of cancer invasion by regulating the expression of mitogen-activated protein 4 kinases 1 or urokinase plasminogen activator receptor." (PMID 32340207, 2020). "Reportedly, DTL overexpression decreased the protein level and accelerated the degradation rate of PDCD4 by ubiquitination and in cancer tissues was significantly upregulated than in normal tissues." (PMID 32596316, 2020). "We investigated the PDCD4 expression level in the GEPIA database and the miR-21-5p expression level in GEDS, which showed a low level of PDCD4 and a high level of miR-21-5p in cancer tissues compared with normal tissues." (PMID 32661236, 2020). "The overexpression of PDCD4 induces apoptosis or cell cycle arrest, inhibits the invasion, proliferation and migration of cancer cells, and increases the sensitivity of cancer cells to antineoplastic drugs." (PMID 31620370, 2019). "Our results elucidated that DTL enhanced the motility and proliferation of cancer cells through degrading PDCD4 to promote the development of cancers." (PMID 31409387, 2019).